MUC5B (mucin 5B, oligomeric mucus/gel-forming)
Diseases named in the same sentence as MUC5B in open-access papers (continued):
Sharing a sentence is not in itself a finding about the gene and the disease.
silicosis (2 papers, 2022 to 2024). Silicosis is a respiratory disease caused by breathing in (inhaling) silica dust. "More studies are needed to better understand if these findings are directly linked to silicosis and should also include data about MUC5B polymorphisms and their implication in the susceptibility of silica-related fibrosis." (PMID 36672608, 2022). "Besides, mucin 5B (MUC5B), neopterin, and matrix metalloproteinases (MMPs) have also been considered as potential biomarkers of silicosis." (PMID 39882130, 2024).
squamous cell carcinoma (2 papers, 2015 to 2025). A carcinoma arising from squamous epithelial cells. "MUC5B expression was observed in 129 of 198 (65.2%) adenocarcinomas and in 4 of 49 (8.2%) squamous cell carcinomas (P < 0.00001)." (PMID 25733373, 2015). "Concretely, Epi2_MUC5B represented adenocarcinoma cell (MUC5B, MUC16, MUC5AC), while Epi4_MYC harbored conventional squamous cell carcinoma features, such as high expression of KRT6A and MYC." (PMID 40657372, 2025).
status asthmaticus (2 papers, 2007 to 2011). An acute exacerbation of asthma, characterized by inadequate response to initial bronchodilators. "However, a low charge MUC5B glycoform was the predominant mucin in mucus that obstructed the airways in an individual who died in status asthmaticus." (PMID 21602926, 2011). "However, biochemical studies on human samples have shown that the aberrant physical properties of the mucus gel obstructing the airways from an individual that died in status asthmaticus are due to MUC5B and not MUC5AC." (PMID 17550583, 2007).
adenoma (1 paper, 2025). A neoplasm arising from the epithelium. "The lower bile viscosity observed in adenomas, potentially linked to reduced mucin secretion, contrasts with cholesterol polyps, where increased mucin expression (e.g., MUC3, MUC5B) raises bile viscosity and contributes to benign pathology." (PMID 40332145, 2025).
allergic asthma (1 paper, 2021). A asthma with a basis in a pathological type I hypersensitivity reaction. "MUC5B, ORMDL3, MUC5AC, CHI3L1, CLCA1, and IL-33 display a distinctly high non-specific relationship with allergic and non-allergic asthma." (PMID 33936056, 2021).
Autoimmunity (1 paper, 2019). The occurrence of an immune reaction against the organism's own cells or tissues. "In addition to the protective role of stimulating the production of many antibacterial proteins (b-defensins, mucins: MUC5AC, MUC5B, S100 calgranulins, lipocalin 2), IL-17 appears to be important in autoimmunity as evidenced by the experimental autoimmune encephalomyelitis (EAE)." (PMID 31468124, 2019).
cervical cancer (1 paper, 2022). A primary or metastatic malignant neoplasm involving the cervix. "Some of the most promising cervicovaginal fluid-based biomarkers for cervical cancer found until now are ACTN4, VTN, ANXA1, ANXA2, CAP1, and MUC5B." (PMID 35645371, 2022).
chronic asthma (1 paper, 2025). An asthma that is characterized by the development of persistent airway inflammation and recurrent attacks of breathlessness and wheezing, which vary in severity and frequency. "The mucus plugs in nonfatal COPD cases had a similar profile (granulocytic, enrichment in MUC5B content, and presence of extracellular DNA traps), indicating that this mucus plug phenotype is a feature of airway mucus plugs in chronic asthma and chronic COPD." (PMID 40091838, 2025).
Constipation (1 paper, 2021). Infrequent or difficult evacuation of feces. "Consistent with that, the subjects recruited in this study all had symptoms of constipation, the SNVs identified in the samples were enriched in the genes associated with gut functions, e.g. the mucin gene (MUC2, MUC3A, MUC4, and MUC5B)." (PMID 33412999, 2021).
cystic teratomas of the ovary (1 paper, 2022). "Among the 15 prevalent mutated genes, 8 with different variants in exons with changes in protein coding are important for the development of mature cystic teratomas of the ovary: FLG, MUC17, MUC5B, RP1L1, NBPF1, SLC29A3, SGK223, and FAM186A." (PMID 36289533, 2022).
ductal adenocarcinoma (1 paper, 2019). "Both membrane-bound (MUC1, MUC3, MUC4) and secreted mucins (MUC2, MUC5AC, MUC5B, MUC6) are upregulated in ductal adenocarcinoma of the breast." (PMID 30682816, 2019).
ductal breast carcinoma (1 paper, 2014). "In breast ductal adenocarcinomas, MUC2 and MUC5AC are localized in cytoplasm with granular staining pattern, whereas distribution of MUC5B expression changes from apical localization in non-malignant breast cells to cytoplasmic and non-apical localization in malignant ductal breast carcinoma." (PMID 25261375, 2014).
Dyskinesia (1 paper, 2023). A movement disorder which consists of effects including diminished voluntary movements and the presence of involuntary movements. "During the repair of the injured mucociliary epithelium in the ALI system, silica-induced NLRP3 inflammasome activation led to either MUC5AC or MUC5B overproduction, multiciliogenesis, and ciliary disorientation, structural defects and dyskinesia." (PMID 37063430, 2023).
endometrioid endometrial adenocarcinoma (1 paper, 2017). "Uterine corpus endometrioid endometrial adenocarcinoma (UEC) appears to acquire more mutations in multiple mucins, including MUC5B and MUC17, which becomes very prominent in stage III." (PMID 28978023, 2017).
esophageal cancer (1 paper, 2018). A primary or metastatic malignant neoplasm involving the esophagus. "Moreover, Cox2 is well known to be involved in CRC carcinogenesis and has been suggested to act by inducing Muc5B and Muc17 secreting cells in the pathogenesis of esophageal cancer." (PMID 29547645, 2018).
invasive carcinoma (1 paper, 2025). A carcinoma that is not confined to the epithelium, and has spread to the surrounding stroma. "Differential gene expression analysis comparing MCNs with their associated invasive carcinomas identified two significantly overexpressed genes in MCNs: OLFM4 and MUC5B." (PMID 40371932, 2025).
lung mucinous adenocarcinoma (1 paper, 2023). "Moreover, HNF-4α is reported as part of the signature genes of invasive lung mucinous adenocarcinoma, together with FOXA3, SPDEF and mucins, such as MUC5AC, MUC5B, and MUC3." (PMID 36674438, 2023).
lymph node metastasis (1 paper, 2025). "Pearson correlation analysis with MUC5B revealed 3,532 genes significantly associated with MUC5B, from which 25 candidate genes were identified based on overlap with lymph node metastasis-associated genes." (PMID 41409294, 2025). "MUC5B was significantly upregulated in LUAD with lymph node metastasis and associated with poor overall and progression-free survival." (PMID 41409294, 2025). "Using a multi-algorithm bioinformatics pipeline combining LASSO, SVM-RFE, and WGCNA, we identified MUC5B as a central gene highly correlated with LUAD samples harboring lymph node metastasis." (PMID 41409294, 2025). "This study aimed to investigate the role of MUC5B in LUAD progression and its potential as a biomarker for lymph node metastasis." (PMID 41409294, 2025). "Furthermore, we calculated the H-score for each sample, and the H-score for MUC5B expression in the group without lymph node metastasis was significantly lower than in the metastasis-positive group (P = 0.0125)." (PMID 41409294, 2025).
middle ear infection (1 paper, 2016). "Finally, MUC5B, the predominant mucin in human COM fluid has also shown to be required for airway defense, with its absence leading to severe middle ear infection in mice." (PMID 27078692, 2016).
mucinous ovarian tumors (1 paper, 2015). "Expression of several gel-forming mucins has been described for mucinous ovarian tumors such as MUC2, MUC5AC and MUC5B." (PMID 26075384, 2015).
Mucinous tumours (1 paper, 2023). "Mucinous tumours overexpress MUC2, a secreted gel-forming mucin that is encoded in the MUC2, MUC5AC, MUC5B and MUC6 genes on chromosome 11." (PMID 36982838, 2023).
Mycoplasma pneumoniae pneumonia (1 paper, 2024). Interstitial pneumonia caused by extensive infection of the lungs (lung) and bronchi, particularly the lower lobes of the lungs, by mycoplasma pneumoniae in humans. "It is recognized in the literature that Mycoplasma pneumoniae pneumonia coincident with plastic bronchitis correlates with modulated expression of inflammatory proteins such as MUC5AC, MUC5B, and layilin." (PMID 38930514, 2024).
prostate tumour (1 paper, 2004). "Overall, MUC2, MUC5B and MUC6 were associated with mucinous morphology, and were expressed in HID prostate tumour variants." (PMID 14760390, 2004). "Using PAC120, a xenograft of a human hormone-dependent prostate tumour, and its hormone-independent variants, we analysed the expression of mucins (MUC1, MUC2, MUC4, MUC5AC, MUC5B, MUC6) by immunohistochemistry or reverse transcriptase (RT)–PCR." (PMID 14760390, 2004).
pterygium (1 paper, 2021). A wedge-shaped fibrovascular lesion arising from the bulbar conjunctiva and extending to the cornea. "An early microarray study reported increased expression of MUC5AC and the related MUC5B in pterygium, while another study reported almost total loss of MUC5AC in pterygium, as assessed by immunostaining." (PMID 34769520, 2021).
Respiratory distress (1 paper, 2019). Respiratory distress is objectively observable as the physical or emotional consequences from the experience of dyspnea. "However, one-fifth to one-quarter of lung-specific Muc5b-deficient mice also exhibited signs of respiratory distress, in agreement with previous reports showing the essential role of Muc5b for mucociliary clearance." (PMID 31699684, 2019).
respiratory infections (1 paper, 2021). "In vivo data indicates a crucial role for MUC5B in the maintenance of healthy interactions between the host and bacteria, as Muc5b-/- but not Muc5ac-/- animals display impaired survival related to respiratory infections." (PMID 34093523, 2021).
rhinitis (1 paper, 2021). An inflammation of the mucous membrane lining the nose, usually associated with nasal discharge. "We also studied altered MUC5AC and MUC5B gene expression consistently observed in rhinitis models, therefore, mucins expression in sinus mucosa was analyzed using RT-qPCR analysis, in particular MUC5AB and MUC5AC expression." (PMID 34638811, 2021).
small cell lung carcinoma (1 paper, 2024). Small cell lung cancer (SCLC) is a highly aggressive malignant neoplasm, accounting for 10-15% of lung cancer cases, characterized byrapid growth, and early metastasis. "In both small cell lung cancer (SCLC) and NSCLC, plasma-derived MUC5B, SELL, and APOH have been shown to be potential biomarkers for the diagnosis of brain and liver metastasis." (PMID 38814362, 2024).
thymoma (1 paper, 2023). A neoplasm arising from the epithelial cells of the thymus. "The mutation frequencies of CDC27 (67% vs. 29%), CTNND2 (33% vs. 4%), KRTAP6‐1 (33% vs. 4%), and RERE (33% vs. 4%) trended to be higher in type B3 thymoma than other subtypes of thymomas, while the mutation frequency of MUC5B (0% vs. 32%) trended to be lower in type B3 thymoma." (PMID 36916520, 2023).
trauma (1 paper, 2023). "Herein, we investigated the formation of bacterial biofilms and MUC5AC and MUC5B gene expression levels in samples from 80 patients admitted for either acute nasal trauma (14 patients, control group) or chronic nasal pathology (66 patients, CRS group)." (PMID 36902594, 2023).
vaginal infection (1 paper, 2024). "Of note, a porous cervical mucus plug deficient in Muc5b leads to preterm birth after vaginal infection in mice." (PMID 38396964, 2024). "Thus, it would be interesting to test whether Tff3-deficient mice show pre-term birth after vaginal infection as reported for Muc5b-deficient mice due to a porous cervical mucus plug." (PMID 38396964, 2024).
infection (65 papers, 2006 to 2025). The state of being infected such as from the introduction of a foreign agent such as serum, vaccine, antigenic substance or organism. "In murine models, MUC5B deficiency led to mucous obstruction of the airways and increased risk of inflammation and infection." (PMID 39769414, 2024). "We speculate that smoking might lead to decreased MUC5B expression in goblet cells, thereby impairing infection control mechanisms and increasing susceptibility to acute and chronic infections, which is one of the characteristic clinical features of COPD." (PMID 39769414, 2024). "As a vital component of the mucosa, H2S-mediated alterations in mucosal functions through muc5ac and muc5b downregulation and may increase the susceptibility of Atlantic salmon to secondary stress and infection." (PMID 36582361, 2022). "In aging lungs, the high expressing MUC5B T-allele may be important for optimal airway defense against infections while it provides an increased risk for IPF in the alveolar compartment." (PMID 34888316, 2021). "The reduced expression of Muc5b transcripts in the skin tissue may lead to impaired mucus production, which may affect the skin barrier function and increase the susceptibility of koi to infection." (PMID 37465154, 2023). "This work shows for the first time, that Pneumocystis associates to increased levels of MUC5B in infants, and replicates this finding in an experimental animal model of naturally acquired primary infection that resembles the mode of contagion and course of the primary infection in humans." (PMID 30765827, 2019). "In our cohort, within a mixed Th1/Th2/Th17 inflammatory milieu, selective MUC5B upregulation likely reflects an infection-driven epithelial response." (PMID 41561092, 2025). "MUC5AC was expressed basally at lower levels, its expression increased transiently with infection, but the absolute RNA levels remained low compared to MUC5B." (PMID 40791384, 2025). "In the lung, a significant upregulation in the mRNA expression of the gel-forming mucins, Muc5ac and Muc5b, trefoil factors, Tff1 and Tff2, and Relm-β, was observed in the acute infection phase." (PMID 39596084, 2024). "The current study revealed a marked down-regulation of Muc5b transcripts in the skin tissue of koi at day 5 post-infection as compared to the control group." (PMID 37465154, 2023). "Regarding mucin expression, we showed that infection by both S and R Mabs inhibited MUC5B and MUC4 expression." (PMID 37619220, 2023). "In order to quantify mucus metaplasia in whole lungs of control and Pou2f3-/- animals, we analyzed gene expression of goblet cell markers, Foxa3, Agr2, Muc5ac, and Muc5b, 51 days post infection." (PMID 36073526, 2022). "Overall, these data indicate that accumulation of Muc5b initiates the muco-obstructive process in the CF lung prior to infection." (PMID 35574458, 2022). "The infection also significantly downregulated the expression of dsc2 when compared to the controls and the expression of muc5b when compared to challenged vaccinated fish." (PMID 35173716, 2022). "Infection by Bp-WT, or the Bp-PT– mutant producing intact CyaA, induced similar Muc5AC and Muc5B production in polarized VA10 cell layers as the treatment with forskolin." (PMID 34445770, 2021). "wdNHBE cells produced an innate immune response to IAV-infection with increased transcription of pro- and anti-inflammatory cytokines and chemokines and the antiviral viperin but reduced expression of the mucin-encoding MUC5B, which may impair mucociliary clearance." (PMID 32599823, 2020). "BALB/c mice were infected with HMPV, and the expression of Muc1, Muc2, Muc4, Muc5ac, Muc5b, Muc15, Muc16, Muc19, and Muc20 were analyzed at 12, 24 and 48 h after infection." (PMID 32899224, 2020).
infection (continued). "Since host genetic polymorphisms have been demonstrated to be associated with vulnerability to human infection, in this study five candidate genes—ACE2, TMPRSS2, CD209, IFITM3, and MUC5B—were selected based on their relevance to the current pandemic." (PMID 33101356, 2020). "CC10 and Muc5b positive cells were detected mainly in Pneumocystis infected epithelial cells at the day 60 of infection." (PMID 31170201, 2019). "14C11 pre-treatment of RV-OVA challenged mice significantly reduced the induction of both MUC5AC and MUC5B mucus proteins 6 days after infection." (PMID 23935498, 2013). "Infection with HIV had occurred at one dilution of 10-40 for MUC5B indicating the potential for a dose–response relationship." (PMID 22929306, 2012). "Inhalation of vMC0, but not vehicle or UV-inactivated vMC0, was accompanied by increased airway fluid myeloperoxidase levels, an indicator of neutrophil activation, increased MUC5B gene expression, and lung edema, a sign of infection-related lung injury." (PMID 22355409, 2012). "The mRNA level of mucin 5B (MUC5b) in the small intestine was very low and unchanged during infection." (PMID 21414188, 2011). "For example, in mice, MUC5B was required for controlling infections in the airways." (PMID 39769414, 2024). "The pattern of expression of airway surface liquid (ASL) homeostasis-associated genes (CFTR, BPIFA1, MUC1, MUC5AC, MUC5B) in the PCLS varied greatly between the three strains, and only infection with strain T15 induced statistically significant changes in this group of genes." (PMID 38276150, 2023). "Deletion of muc5ac in mice does not cause pulmonary problems in rodents, but deletion of muc5b was shown to have severe, negative consequences regarding infection control and MCC." (PMID 36675209, 2023). "Furthermore, acute RSV infection increased expression of mucin genes Muc5b and Muc5ac in the lung, suggesting enhanced mucus production and goblet cell hyperplasia with infection." (PMID 37795093, 2023). "Furthermore, mucosal response of mucin-encoding genes (Muc2 and Muc5b) in AS and koi upon CEV genogroup IIa infection in gill, gut and skin tissues was evaluated." (PMID 37465154, 2023). "The induction of mucus secretion associated to mild infection by Pneumocystis has been described as part of a STAT6/FoxA2 pathway immune response, leading to the increment of the levels of the two most relevant mucins of the airways: Muc5ac and Muc5b." (PMID 37108906, 2023). "However, a significant down-regulation of Muc5b transcripts, was observed in the skin tissues of koi on day 5 post-infection compared to the control." (PMID 37465154, 2023). "The two muc5 genes, muc5ac and muc5b, play an essential role in airway defence in human and mouse, particularly in producing mucin glycoproteins that protect the respiratory surfaces from infections." (PMID 36582361, 2022). "Hence, the presence of Muc5B in the lung is essential for controlling infections, maintaining immune homeostasis, and mucociliary clearance." (PMID 34888316, 2021). "This could help to understand part of this mechanism and the role of MUC5B in ANDV-infections in humans." (PMID 33224896, 2020). "Our data indicate that the MUC expression by RSV and hMPV differs significantly, as we observed a stronger induction of MUC8, MUC15, MUC20, MUC21, and MUC22 by RSV infection while the expression of MUC1, MUC2, and MUC5B was dominated by the infection with hMPV." (PMID 25977598, 2015). "An investigation of the variation in the genetic and protein structure of mucins MUC5B and MUC7 and their association with infection with HIV is a study that could be engendered by these findings." (PMID 22929306, 2012). "PCR was done on tandem repeat regions of MUC5B and MUC7 DNA to investigate whether any association existed between gene polymorphism and susceptibility to infection." (PMID 22929306, 2012).